BTK (Bruton tyrosine kinase)
Diseases named in the same sentence as BTK in open-access papers (continued):
Sharing a sentence is not in itself a finding about the gene and the disease.
neutropenia (14 papers, 2020 to 2025). A decrease in the number of neutrophils found in the blood. "Matching this, BTK deficiency has been associated with reduced number of monocytes, macrophages as well as granulocytes arresting in a pre-mature stage causing neutropenia in different studies." (PMID 36911665, 2023). "However, long-term CLL, immunosuppressive therapies, neutropenia, and prior use of azoles and other antimycotic agents were risk factors for mucormycosis; BTK inhibitor could also be added as another novel risk factor." (PMID 37754514, 2023). "The well documented adverse events observed with BTK pathway inhibition predominate, including neutropenia, infection, contusion, and fatigue." (PMID 39941922, 2025). "Neutropenia occurs in approximately 10–25% of cases, possibly resulting from defective Fc receptor signaling in BTK-dependent myeloid cells." (PMID 40863427, 2025). "Thrombocytopenia and neutropenia were commonly observed in patients with CLL on BTK inhibitor treatment." (PMID 37845755, 2023). "The most common AEs after treatment with new-generation covalent BTK inhibitors are neutropenia, thrombocytopenia, rash, bruises, leukopenia, and so on, which can be managed according to the instructions and related guidelines." (PMID 37845755, 2023). "Stratification of neutropenia events by severity revealed higher incidence of grade 1 – 2 neutropenia among SYK and/or BTK inhibitors group in comparison to placebo group (RR 4.24; 95%CI: 1.00 – 18.01, p=0.05, I2 = 0%, random-effect model)." (PMID 41458387, 2025).
acute myeloid leukemia (13 papers, 2014 to 2026). Acute myeloid leukemia (AML) is a group of neoplasms arising from precursor cells committed to the myeloid cell-line differentiation. "This suggested the role of BTK as a potential therapeutic target in acute myeloid leukemia, so preclinical and clinical studies are performed to estimate the BTK selective inhibitor ibrutinib usage in the treatment of AML." (PMID 34440129, 2021). "Both compounds very effectively reduced expression of BTK within 4 h in acute myeloid leukemia (AML)-derived MOLM-14 cells with little effect on other potential PROTAC targets investigated, including AURKA." (PMID 32924028, 2020). "Since BTK is expressed in myeloid cells, we evaluated ibrutinib in acute myeloid leukemia (AML)." (PMID 26624983, 2016). "Given the reported expression and constitutive activation of BTK in acute myeloid leukemia (AML) cells, there has been recent interest in investigating the anti-AML activity of ibrutinib." (PMID 26624983, 2016). "Abivertinib, an inhibitor of Bruton's tyrosine kinase (BTK), in combination with HHT have synergistic effect in treating acute myeloid leukemia cells." (PMID 32733254, 2020). "ARQ 531 could target multiple pathways including BTK, MYB, AKT, ERK, and other pathways in acute myeloid leukemia (AML)." (PMID 33676527, 2021).
lupus nephritis (13 papers, 2013 to 2026). Glomerulonephritis in the context of systemic lupus erythematosus. "Another irreversible BTK inhibitor, BI-BTK-1, ameliorated multiple pathological endpoints associated with kidney disease in two distinct murine models of spontaneous lupus nephritis in mouse models of SLE: NZB × NZW F1 (NZB/W) and MRL/lpr." (PMID 35628931, 2022). "In humans, higher BTK expression in B cells from peripheral blood is associated with lupus nephritis." (PMID 29884225, 2018). "In SLE patients, increased BTK expression in peripheral blood was associated with lupus nephritis." (PMID 35729649, 2022). "Newer BTK inhibitors like zanubrutinib is currently undergoing a phase 2 clinical trial in patients with lupus nephritis (NCT04643470), while BI-BTK-1 showed promising preclinical results in a murine model of lupus nephritis." (PMID 41573545, 2025). "This classical model of lupus nephritis is responsive to treatments targeting IL-6, Bruton’s tyrosine kinase (BTK) inhibitor, CD20, BAFF, glucocorticoid receptor, and CTLA-4." (PMID 39452087, 2024). "In agreement with the previous studies, BTK inhibitor (BTKB66) treatment was effective in treating lupus nephritis in terms of reducing renal damage both functionally and histologically, accompanied by significant decrease in proteinuria." (PMID 35874767, 2022). "BTK inhibitors (PF-06250112, M7583, BI-BTK-1, RN-486, ibrutinib, poseltinib, and evobrutinib) have demonstrated the prevention or amelioration of lupus nephritis and other SLE symptoms in mouse models of SLE." (PMID 35628931, 2022). "BTK is normally silenced on the Xi in human fibroblasts, yet it is overexpressed in PMBCs of patients with lupus nephritis, suggesting that some immune cells may have reactivated BTK from the Xi." (PMID 41574968, 2026). "SYK, BTK, PDGFR, EFGR, DDR1 and Janus kinase are implicated in the pathogenesis of lupus nephritis." (PMID 28391340, 2017).
viral infection (12 papers, 2019 to 2025). "Whilst this might be a direct consequence of BTK deficiency, it is possible that this inflammation is a post-viral infection phenomenon." (PMID 34164761, 2021). "However, the inhibitory effects of BTK inhibitors (BTKi) on innate and humoral immunity may heighten susceptibility to certain viral infections." (PMID 40833106, 2025). "In our study, we found that genetic manipulation of BTK affected the replication of both VACV and MPXV, further demonstrating the involvement of BTK as an immune regulator during virus infection." (PMID 40833106, 2025). "Upon viral infection, Bruton tyrosine kinase (BTK), which is downstream of toll-like receptors (TLRs), is activated and initiates NF-κB signaling." (PMID 34001144, 2021). "As BTK is a homologous protein of Syk, we hypothesized that BTK may facilitate viral infection by suppressing type I IFN responses in infected cells." (PMID 40833106, 2025). "BTK plays a crucial role in regulating the innate immune system against viral infection." (PMID 36183125, 2022). "Furthermore, BTK regulates the immune response in microbial and viral infections through B cells and myeloid cells such as monocytes and macrophages." (PMID 33818636, 2021). "The subcellular localization of BTK in HeLa and THP-1 cells upon viral infection was also quantified." (PMID 40833106, 2025). "As an example, kinases like the tyrosine kinases, Rho kinase, Bruton tyrosine kinase, ABL kinases, and NAK kinases play an important role in the modulation of signaling pathways involved in both cancers and viral infections such as COVID." (PMID 38646411, 2024). "These genes include TLR8, which is involved in Th1 differentiation, relevant in viral infections, or BTK (Bruton Tyrosine Kinase), involved in downstream signaling events of the B-cell receptor." (PMID 34349112, 2021). "Remarkably, in the absence of ibrutinib during viral infection, suppression of BTK by siRNA significantly induced NF-κB expression, and supplementation of BTK reversed this phenomenon in a dose-dependent manner, and similar results were observed for IFNβ." (PMID 40833106, 2025). "In the absence of ibrutinib during viral infection, suppression of BTK by siRNA significantly induced NF-κB expression, and supplementation of BTK reversed this phenomenon in a dose-dependent manner, and similar results were observed for IFNβ." (PMID 40833106, 2025). "The literature has documented cases of fungal and viral infections, but there have been no reports of parasitic infections following targeted therapy with the combination of rituximab and BTK inhibitors." (PMID 39993065, 2025).
allergic disease (11 papers, 2016 to 2024). An immune response that occurs following re-exposure to an innocuous antigen, and that requires the presence of existing antibodies against that antigen. "In particular, mast cell Fc-epsilon receptor (FcεR) signaling is likewise regulated by BTK, making BTK inhibitors a potential treatment for immunoglobulin E (IgE)-related disorders such as allergies, asthma, and dermatitis." (PMID 36903645, 2023). "BTK inhibitors offer several advantages over other drugs commonly used for treating allergic diseases, including the inhibition of IgE-FcεRI-mediated activation of both mast cells and basophils." (PMID 35628931, 2022). "Because BTK plays an important role in B cell receptor signaling and therefore affects plasma B cell survival, exploratory endpoints included markers of humoral immunity function and allergy." (PMID 37384412, 2023). "Beyond allergic disease, BTK has many roles, especially in B cell proliferation and malignancy." (PMID 36230993, 2022). "The clinical value of BTK inhibition in the context of allergic diseases remains to be determined." (PMID 28328081, 2017). "Further studies are needed to delineate the safety and utility of prolonged administration of BTK inhibitors before these drugs could be used chronically in healthy patients for allergy indications, for example, to prevent reactivity from an accidental food exposure." (PMID 37384412, 2023). "In particular, those with hypomorphic BTK variants that facilitate the production of some immunoglobulins may have an allergy phenotype with no history of severe infection." (PMID 35273610, 2022). "Bruton's tyrosine kinase (BTK) is an essential enzyme for IgE-mediated signaling pathways, and is an ideal pharmacologic target to prevent allergic reactions." (PMID 37066249, 2023). "Preclinical studies and clinical trials suggest that BTK inhibitors can be useful for the treatment of IgE-dependent anaphylaxis, food and drug allergy, asthma, CSU, and other allergic diseases." (PMID 35628931, 2022). "The effects of these BTK inhibitors were dose dose‐dependent and occurred at pharmacological concentrations which may have clinical implications and may pave the way to the development of new antiallergic treatment concepts in patients with IgE‐dependent allergies." (PMID 28328081, 2017). "However, BTK inhibitors would not likely have efficacy on IgE-independent allergic diseases, as BTK is not known to be involved in IgE-independent pathways of mast cell or basophil activation." (PMID 34778053, 2021).
Burkitt lymphoma (11 papers, 2013 to 2023). A rare form of malignant mature B-cell non-Hodgkin lymphoma. "In addition, our study focused on investigating the potential therapeutic efficacy of simultaneous targets of EZH2 and BTK in Burkitt’s lymphoma and exploring the underlying apoptotic pathways associated with this drug combination." (PMID 37752998, 2023). "TL-895 inhibited BTK auto-phosphorylation at Y223 after BCR stimulation with anti-IgM in the human Burkitt’s lymphoma B-cell line Ramos in a concentration-dependent manner with an IC50 between 1 and 10 nM." (PMID 37989777, 2023). "Given the central role of BTK in lymphomagenesis, BTK inhibitors have demonstrated efficacy in B cell malignancies, particularly in subsets of Burkitt’s lymphoma." (PMID 37752998, 2023). "In conclusion, our study provides compelling evidence for the therapeutic potential of simultaneous EZH2 and BTK targets in Burkitt’s lymphoma." (PMID 37752998, 2023). "In our study, we aimed to explore the synergistic effects of combining the BTK inhibitor Ib with dEZH2 in the context of Burkitt’s lymphoma." (PMID 37752998, 2023). "Recently, a light-controllable PROTAC against BTK, named pc-PROTAC3, was reported to efficiently degrade BTK in Ramos Burkitt’s lymphoma (BL) cells upon light exposure." (PMID 32718354, 2020). "It exhibited activities in degradation of wild-type and mutant BTK and inhibited cell proliferation in Burkitt lymphoma and chronic lymphocytic leukemia cells." (PMID 32404196, 2020). "We next investigated CHMFL-BTK-11′s inhibitory efficacy in the Ramos cell line (Burkitt lymphoma cells) which is characterized with high expression of BTK kinase." (PMID 28352114, 2017). "Furthermore, our study sought to explore the potential synergistic effects of combining these therapies with Ibrutinib, a widely used Bruton’s tyrosine kinase (BTK) inhibitor in Burkitt’s lymphoma treatment." (PMID 37752998, 2023). "Based on our assumption that the BTK inhibitor Ib, which can be used in some subsets of Burkitt’s lymphoma, could have a synergistic effect when combined with dEZH2, we tested the combination therapy of Ib with iEZH2 or Ib with dEZH2." (PMID 37752998, 2023). "The small molecule inhibitor abolishes BCR signaling in Ramos human Burkitt's lymphoma cell line by covalently binding to BTK, and selectively inhibits its autophosphorylation as well as activation of PLCγ2 and other downstream substrates of BTK." (PMID 23958373, 2013). "In Burkitt lymphoma cells, the B-cell receptor signaling pathway was the most enriched in SYK targets, including the BTK protein tyrosine kinase." (PMID 33670716, 2021). "Specifically, Burkitt’s lymphoma cells that exhibit dependency on BCR signaling for growth and survival could benefit from BTK inhibition." (PMID 37752998, 2023).
colitis (11 papers, 2020 to 2025). Inflammation of the colon. "Here, we do not completely rule out the possibility that gut microbiota variation contributes to increased colitis risk in BTK-deficient mice, as 16 S rRNA sequencing analysis only assesses the gut bacteria." (PMID 33931590, 2021). "Surprisingly, we found that after cohousing, BTK-deficient mice were still more susceptible to DSS-induced colitis, as indicated by the substantially higher rate of weight-loss and mortality." (PMID 33931590, 2021). "Here, for the first time, we demonstrate unequivocally that Th1 response is selectively enhanced in the gut mucosa of BTK-deficient mice, thus predisposing them to colitis." (PMID 33931590, 2021). "We further demonstrated that the gut LP of BTK-deficient mice have elevated Th1 cells, which are likely responsible for their enhanced colitis risk." (PMID 33931590, 2021). "As compared with WT controls, BTK-KO mice manifested early-onset colitis with significantly more weight loss, higher mortality rate and greater shortening of colons." (PMID 33931590, 2021). "Mechanistic insights from previous studies have also highlighted impaired production of type I and III interferons in XLA patients following enteroviral infections, as well as dysregulated IL-1β signaling and NLRP3 inflammasome hyperactivation in BTK-deficient colitis models." (PMID 40963632, 2025). "BTK deficiency has been shown in various experiments to lead to severe colitis." (PMID 38736878, 2024). "To explore whether BTK-deficient mice harbor a disturbed gut microbiota driving colitis development, we first analyzed whether BTK-deficiency affects gut mucosal IgA response, an important regulator of microbiota commensalism." (PMID 33931590, 2021). "However, such interpretation is confounded by the ablation of regulatory B cells (Bregs) in the BTK-deficient individuals and potential involvement of other inflammasomes in colitis (such as NLRC4, NLRP6, pyrin or AIM2)." (PMID 34485307, 2021). "Here, we show that BTK-deficiency promotes IBD progression in a mouse model of colitis." (PMID 33931590, 2021). "In this study, we demonstrated that BTK-deficiency exacerbated DSS-induced colitis in the mouse." (PMID 33931590, 2021). "We next induced acute colitis in co-housed WT and BTK-KO mice by DSS-treatment and determined their disease susceptibility." (PMID 33931590, 2021). "Collectively, these data indicate that BTK-KO mice developed more severe colitis than WT mice when treated with DSS." (PMID 33931590, 2021). "BTK-deficient mice show increased DSS- or 2,4,6-trinitrobenzene sulfonic acid (TNBS)-induced colitis, which can be ameliorated by administration of IL-1β monoclonal antibody." (PMID 33808793, 2021). "To address if the exacerbated colitis in BTK-KO mice was due to this factor, we co-housed WT and BTK-KO mice to normalize their gut microbiota." (PMID 33931590, 2021). "The propensity for colitis development in BTK-deficient mice is not due to shifts in their gut microbiota." (PMID 33931590, 2021). "Hence, we assessed if the severe colitis in BTK-KO mice was triggered by shift in their microbiota." (PMID 33931590, 2021). "We show here that mice lacking BTK had increased susceptibility to DSS-induced colitis." (PMID 33931590, 2021). "Interestingly, the increased colitis susceptibility of BTK-deficient mice is not caused by gut microbiota changes but rather arises from enhanced pro-inflammatory Th1 response." (PMID 33931590, 2021). "Our cohousing experiments further showed that the increased colitis risk in BTK-deficient mice was not induced by a colitogenic microbiota, as a reshaped microbiota similar to that seen in the WT mice did not rescue the severe disease phenotype in BTK-deficient mice." (PMID 33931590, 2021).
colitis (continued). "Moreover, we found that normalization of BTK-deficient mice gut microbiota by cohousing them with WT mice did not reduce their enhanced susceptibility to DSS-induced colitis, thus ruling out altered microbiota as the main contributing factor for the more severe colitis in these mice." (PMID 33931590, 2021). "The Rag2−/− mouse model of T-cell-mediated colitis also revealed a nonredundant role of BTK in CD4+ T-cell responses." (PMID 31431692, 2020).